PPARG (peroxisome proliferator activated receptor gamma)
Diseases named in the same sentence as PPARG in open-access papers (continued):
Sharing a sentence is not in itself a finding about the gene and the disease.
follicular thyroid carcinoma (37 papers, 2004 to 2025). "A unique molecular characteristic linked to follicular thyroid cancer is the rearrangement of PAX8/PPARγ." (PMID 38501105, 2024). "PAX8/PPARG rearrangements are present in classic follicular carcinoma, follicular-variant-PTC and OCC, suggesting potential implications in tumor evolution, invasion and metastasis." (PMID 38277563, 2024). "The peroxisome proliferator receptor gamma (PPARγ) alteration associated with steroids transcriptional factors was detected only in follicular thyroid cancer and follicular adenoma." (PMID 36980957, 2023). "Four molecular alterations, BRAF and RAS point mutations, and RET/PTC and PAX8/PPARγ rearrangements, are the most frequent causes of thyroid papillary and follicular carcinomas." (PMID 29721199, 2018). "PAX8/PPARγ mutations were found in one follicular carcinoma and two follicular adenomas, respectively." (PMID 26695504, 2016). "PPARγ has also been linked with thyroid pathology since the discovery of a PAX8/PPARγ rearrangement in follicular thyroid carcinomas." (PMID 22654559, 2011). "Conversely, in primary follicular thyroid carcinomas, RAS variants and PAX8/Peroxisome Proliferator-Activated receptor γ (PPARγ) fusions are found in approximately 80% of cases." (PMID 36975488, 2023). "Follicular thyroid cancer and the follicular variant of papillary thyroid carcinoma are associated with mutually exclusive mutations of RAS or the paired box 8-peroxisome proliferator-activated receptor gamma (PAX8–PPARG) fusion oncogene." (PMID 34680488, 2021). "The most frequent genetic alterations in follicular carcinomas are point mutations of RAS and the PAX8/PPARγ rearrangement." (PMID 29721199, 2018). "The PAX8/PPARγ fusion oncogene has been identified only in follicular carcinomas and in a small fraction (about 13%) of follicular adenomas." (PMID 29721199, 2018). "The most common genetic mutations in papillary and follicular thyroid cancers are point mutations of the BRAF or RAS genes, while the most common chromosomal alterations are RET/PTC and PAX8/PPARγ rearrangements." (PMID 29721199, 2018). "A chromosomal rearrangement of the PAX8 gene with PPARγ (PAX8–PPARγ) is observed in about 36–50% of follicular thyroid cancer cases and 0.8% of papillary thyroid cancer." (PMID 29085335, 2017). "A chromosomal translocation fusing the genes PAX8 and PPARG is found in 30% of follicular thyroid carcinomas." (PMID 28008156, 2017). "The PAX8- peroxisome proliferator-activated receptor gamma (PPARG) gene fusion is a consequence of a translocation between chromosomes 2 and 3, and is found in ~30% of follicular thyroid carcinomas and ~5% of follicular variant papillary carcinomas." (PMID 26595524, 2015). "Recent studies in this field demonstrated PAX8/PPARγ rearrangement in 25%-63% of patients with follicular carcinoma and 37.5% of those suffering from papillary carcinoma." (PMID 23815863, 2013). "PAX8/PPARγ is found in 30–40% of conventional-type follicular carcinomas, and with lower prevalence in oncocytic carcinomas in a small fraction of follicular adenomas and occasionally in the follicular variant of papillary carcinoma." (PMID 22654559, 2011). "It is most often expressed in follicular carcinomas and exerts a dominant-negative effect on wild-type PPARγ, and stimulates transcription of PAX8-responsive promoters." (PMID 18989374, 2008). "A PAX 8/PPARγ rearrangement has been noted inhalf of all follicular thyroid cancers, in which the resulting protein has aloss of PPARγ function." (PMID 19125177, 2008). "The recent discovery of the PAX8/PPARγ translocation in follicular thyroid carcinoma has promoted progress in the role of PPARγ as a tumor suppressor and potential therapeutic target." (PMID 18989374, 2008).
follicular thyroid carcinoma (continued). "It has been reported that follicular adenomas with the PAX8/PPARγ rearrangement are likely to be follicular carcinomas, as these genetic abnormalities are presumed to be involved in the progression from follicular adenoma to follicular carcinoma." (PMID 38791384, 2024). "PAX8/PPARγ is expressed in 30–35% of follicular thyroid carcinoma and 2–13% of follicular adenomas." (PMID 25866814, 2015). "A recent study suggested that the nuclear peroxisome proliferator-activated receptor γ (PPARγ) could activate CHK2 in the development of follicular thyroid cancer." (PMID 23593005, 2013). "RAS genes and PAX8/PPARγ rearrangement are found more in follicular carcinomas." (PMID 23717622, 2013). "Recent studies demonstrated that screening for RAS, RET/PTC, and PAX8/PPARγ gene alterations in addition to BRAFV600E provided significant improvement in the diagnostic accuracy of FNA cytology, particularly in the categories of indeterminate cytology and follicular carcinomas." (PMID 34851044, 2022). "In the case of thyroid follicular cancer, a chromosomal translocation and fusion of PAX8 gene with PPARγ results in a malignant phenotype, suggesting a link of PPARγ to cancer growth." (PMID 15583697, 2005). "Chromosomal alterations of PPARγ,resulting in the expression of the fusion protein PPFP, may be an early event in thedevelopment or progression of follicular thyroid cancer and perhaps the follicularvariant of papillary cancer." (PMID 18989374, 2008).
ischemic stroke (37 papers, 2012 to 2026). A stroke disorder caused by obstruction of blood flow to the brain, due to thrombotic (local blood clot formation) or embolic (due to a blood clot or other material traveling from another site) event. "The results provide novel insight into the neuroprotective mechanisms linked to the activation of cerebral PPARγ and the rationale for conducting additional clinical trials investigating the use of pioglitazone in acute treatment of patients suffering from ischemic stroke." (PMID 33864097, 2021). "In ischemic stroke, Bcl-2 phosphorylation or peroxisome proliferator-activated receptor gamma (PPAR-γ) activation can disrupt or modulate the Bcl-2–Beclin1 interaction, thereby influencing autophagy induction and progression." (PMID 40943626, 2025). "The disruption of S100A9 in M/M ameliorates brain injury through the STAT6/PPARγ pathway in ischemic stroke." (PMID 39107960, 2024). "Our current research findings reveal that S100A9‐mediated M/M polarization exacerbates neuroinflammatory injury through the STAT6/PPARγ pathway in ischemic stroke." (PMID 39107960, 2024). "In ischemic stroke, traumatic brain injury, and spinal cord injury, the activation of PPARγ attenuates inflammation by inhibiting the expression of proinflammatory mediators in microglia and macrophages." (PMID 36834611, 2023). "FGF21 can protect against BBB disruption by activating PPARγ after ischemic stroke in T2DM db/db mice." (PMID 36594101, 2023). "For instance, CBD induced neuroprotection in ischemic stroke though PPARγ involvement, which seemed to be also related to the antiseizure properties of the ghrelin receptor antagonist EP-80317, and of the ketogenic diet." (PMID 35631322, 2022). "For example, a current study showed that 10-O-(N,N-dimethylaminoethyl)-ginkgolide B methanesulfonate (XQ-1H) promoted anti-inflammatory microglial polarization through activation of the PPARγ signaling pathway after ischemic stroke." (PMID 34276530, 2021). "PPARG plays an important role in the inflammatory response after ischemic stroke and can target EGR-1 to inhibit the inflammatory response after ischemic stroke, and its activation inhibition can increase M2 and decrease M1 microglia/macrophage." (PMID 34603472, 2021). "Surprisingly, lower angiogenesis and neurogenesis were verified in myeloid cell–specific peroxisome proliferator-activated receptor γ (PPARγ) knockout (mKO) mice than in wild-type mice 5 days after ischemic stroke." (PMID 33193029, 2020). "Others have reported that PPARγ activity in brain tissue is dramatically declined after ischemic stroke, which leads to downregulation of tight junction (TJ) proteins and subsequent BBB leakage." (PMID 32012810, 2020). "During the postischemic, reperfusion phase, pioglitazone, a synthetic agonist for PPARγ, also improves recovery from ischemic stroke." (PMID 29104807, 2017). "RSG, an agonist of peroxisome proliferator-activated receptor-gamma (PPARγ), has been demonstrated to be effective in the treatment of ischemic stroke." (PMID 26021445, 2015). "And the damaged area of ischemic stroke was significantly reduced after PPARγ agonist intervention while it was significantly increased by the PPARγ antagonist modulation." (PMID 26844229, 2015). "In conclusion, the major discovery of the current study is to demonstrate the protective effects of MA, a novel resveratrol oligomer from H. hainanensis, in ischemic stroke by inhibiting inflammation through activation of PPARγ." (PMID 25889216, 2015). "PPARγ-mediated 14-3-3ε upregulation also plays a pivotal role in neuroprotection and the beneficial effects of rosiglitazone against ischaemic stroke." (PMID 23526793, 2013). "The current state of the literature provides significant evidence of a statistically relevant association between SNPs of the IRF6 gene and ischemic stroke, further corroborated by recent studies identifying a role for IRF6 as a regulator of PPARγ in the post-ischemic response." (PMID 40149423, 2025).
ischemic stroke (continued). "Moreover, our research has identified that S100A9‐mediated M/M polarization aggravates neuroinflammatory injury via the STAT6/PPARγ pathway in ischemic stroke, providing a new understanding of the molecular mechanisms involved." (PMID 39107960, 2024). "Our findings suggest that PPARγ is an essential contributor to anti‐inflammatory responses, and treatment with PPARγ agonists may benefit ischemic stroke." (PMID 39107960, 2024). "In addition, PPARγ is involved in the long-term promotion of cellular and tissue repair and the rescue of brain cells following injury including ischemic stroke, hemorrhagic stroke, traumatic brain injury, and spinal cord injury." (PMID 36834611, 2023). "In addition, PPARG plays a role in angiogenesis after ischemic stroke and can promote functional recovery." (PMID 34603472, 2021). "With the exception of ischemic stroke, for which several large trials have reported promising outcomes with pioglitazone and rosiglitazone, the results from clinical trials for PPARγ agonists in CNS disease have not typically lived up to the promising preclinical data." (PMID 36834611, 2023). "Importantly, according to upstream regulator analysis, PPARγ and STAT6 may play pivotal roles in determining the pro-efferocytic transcriptome of macrophages in the brain 5 days after ischemic stroke." (PMID 33193029, 2020).
liver cancer (37 papers, 2011 to 2026). An epithelial or non-epithelial malignant neoplasm that arises from the liver. "In contrast, in liver cancer, elevated levels of PPARγ nuclear condensates are associated with resistance to immune checkpoint blockade therapy (ICB)." (PMID 38383403, 2024). "In diabetic patients, the use of PPARγ agonists (pioglitazone and rosiglitazone) is associated with decreased liver cancer incidence." (PMID 27769068, 2016). "A particularly intriguing aspect of SPP1+ TAMs in liver cancer is their terminally differentiated state and their dependency on PPARγ, a transcription factor known for its role in M2‐like macrophage polarisation and adipogenesis." (PMID 40395129, 2025). "We also observed enhanced mRNA levels of these downstream target genes of the PPARγ signaling in the MYC-ON mouse liver cancer treated with Arf1 inhibitors." (PMID 39872623, 2023). "Specifically, patients with liver cancer with high PPARG expression exhibited a significant increase in the proportions of macrophages M1, macrophages M2, T cells (δ and γ), and T cell regulatory (Tregs)." (PMID 38044948, 2023). "16, 92, 93, 94 To some extent, they can also demonstrate the potential of PPARγ natural agonists as anti‐liver cancer agents." (PMID 32031298, 2020). "Consistent with previous findings, we found that PPARG activation in liver cancer cells by E2 and ER agonists inhibits proliferation, induces cell cycle arrest, and induces apoptosis through caspase 3 activation." (PMID 30510575, 2018). "More studies have suggested that after being treated with PPARγ agonists, such as rosiglitazone, the growth of liver cancer cells in vitro can be blocked at Phase G1." (PMID 29483923, 2018). "Inspired by the evidence that phosphorylation of PPARγ at Ser84 was significantly up-regulated in liver cancer tissue, we are interested in determining the involvement of PPARγ phosphorylation during HCC development." (PMID 27769068, 2016). "In addition, FABP1, HO-1, LXR-α, PPAR-alpha (PPARα), and PPARγ have been affected by MPs in liver cancer cells." (PMID 41378310, 2025). "Cells with elevated PPARγ expression in liver cancer displayed increased drug sensitivity." (PMID 38044948, 2023). "The expression of ADGRG2 was negatively correlated with the PPAR signaling pathway, and one of the members of PPARγ mainly mediated the antiangiogenic process and may be a therapeutic target for liver cancer." (PMID 38069309, 2023). "Schaefer80 and Lin81 found that PPARγ is highly expressed in hepatic cancer tissues and in HCC cell lines, and the inhibition of PPARγ function could cause HCC cell death." (PMID 32031298, 2020). "In this study, we showed that PPARγ agonists (15d-PGJ2 or rosiglitazone) effectively inhibited stem cell-like properties in human liver cancer cells, and that NADPH oxidase-2 (NOX2)-induced reactive oxygen species (ROS) generation functioned as a key downstream event." (PMID 24023668, 2013). "Combinatory application of an AKT inhibitor and a PPARγ agonist may provide a new strategy for inhibition of stem cell-like properties in HCCs and treatment of liver cancer." (PMID 24023668, 2013). "Our results indicate that PPARγ is key in this interaction between ILC2s and cancer cells, by supporting ILC2s in their pro-tumoral functions, that might be conserved across different IL-33 dependent tumors, such as breast and liver cancer." (PMID 33953160, 2021). "In summary, seven of the genes (VEGFA, CTNNB1, SPP1, PPARG, RAC1, HSP90AA1, and LGALS3) were highly unregulated in patients with liver cancer." (PMID 35069936, 2022). "Momordin Ic has been reported to suppress liver cancer cell invasion via COX-2 inhibition and PPARγ activation." (PMID 32560563, 2020).
liver cancer (continued). "Consequently, the combined administration of PPARγ antagonists and ICB therapy proves effective in inhibiting liver cancer resistance to ICB, mediating the normalization of the tumor microenvironment (TME), and contributing to cancer treatment." (PMID 38383403, 2024). "The antitumorigenic effect of PPARγ agonists in several liver cancer cell lines has been previously demonstrated although there have been no studies to mechanistically define the role of PPARγ in hepatocarcinogenesis." (PMID 22966221, 2012). "Moreover, the expression levels of PPARα, PPARγ, FABP1, FABP4, and FABP5 were downregulated in GL22-treated xenograft tumors, indicating that GL22 exerted a significant anticancer effect against liver cancer in vivo mediated by PPAR–FABPs signaling pathway." (PMID 29880886, 2018). "Intriguingly, the CCA marker KRT19 and the PROX1 targets PRRX1 and PPARG exhibited a negative correlation with PROX1 expression in tumor tissue, suggesting that PROX1 could regulate liver cancer plasticity and HCC versus CCA fate." (PMID 39948437, 2025).
nonalcoholic steatohepatitis (36 papers, 2012 to 2026). "It has been demonstrated that the PPARγ agonist rosiglitazone can reduce hepatic inflammation and associated biomarkers in a methionine- and choline-deficient diet mouse model of nonalcoholic steatohepatitis." (PMID 31295333, 2019). "This was consistent with a previous study that showed that interference with miR-21-5p in human and mouse nonalcoholic steatohepatitis cells inhibited PPARγ-mediated adipogenesis." (PMID 39336734, 2024). "These PPARγ agonists have been used in the treatment of hyperlipidemia and hyperglycemia and for non-alcoholic steatohepatitis (NASH) and have been proposed for the treatment of CNS diseases." (PMID 36834611, 2023). "Clinical trials are currently underway to investigate the beneficial effects of PPARγ agonists on NAFLD/nonalcoholic steatohepatitis." (PMID 37190114, 2023). "The present study focuses on the role of TWIST1, TWIST2 and PPARγ in nonalcoholic steatohepatitis progression." (PMID 33879188, 2021). "Recent studies have reported beneficial hepatic effects of PPARγ agonists in reversing nonalcoholic steatohepatitis (NASH) in patients, reducing liver inflammation, fibrosis and triglyceride content." (PMID 29883404, 2018). "Clinical trials assessing the treatment of fibrotic diseases with PPARγ agonists have largely been limited to patients with non-alcoholic steatohepatitis (NASH), and the results have been decidedly mixed." (PMID 28620300, 2017). "PPARα and PPARγ agonists have the potential to correct non-alcoholic steatohepatitis damages." (PMID 34593018, 2021). "ACLP activates HSCs by inhibiting PPARγ through activation of WNT signaling, which leads to exacerbation of nonalcoholic steatohepatitis (NASH)." (PMID 37686580, 2023). "The induction of various miRNAs expressed in nonalcoholic steatohepatitis (NASH) and fibrosis correlated with PPARγ downregulation and overexpression of profibrogenic markers like α-SMA." (PMID 28167956, 2017). "In addition, pirfenidone prevented myocardial steatosis and fibrosis in a mouse model of nonalcoholic steatohepatitis (NASH) by overexpressing PPARα, PPARγ, ACOX1, and CPT1A protein levels and decreasing Timp1, Col I, Col III mRNA levels." (PMID 33809061, 2021).